NFAT5 (nuclear factor of activated T cells 5)
Diseases named in the same sentence as NFAT5 in open-access papers (continued):
Sharing a sentence is not in itself a finding about the gene and the disease.
Parkinson disease (3 papers, 2021 to 2025). A progressive degenerative disorder of the central nervous system characterized by loss of dopamine producing neurons in the substantia nigra and the presence of Lewy bodies in the substantia nigra and locus coeruleus. "For instance, the miR-29c-3p/NFAT5 axis was reported to be associated with the occurrence of Parkinson’s disease." (PMID 34064510, 2021). "LPS-stimulated BV-2 cells mimic Parkinson's disease-associated microglial inflammation, with miR-29c inhibiting NLRP3 inflammasome activation by targeting NFAT5." (PMID 40421201, 2025). "In previous reports, miR-29c was proved to target specific protein-1 (SP1) and nuclear factor of activated T cells 5 (NFAT5) to inhibit the inflammatory response in Parkinson's disease." (PMID 35433915, 2022). "In Parkinson's disease, NFAT5 emerges as a potential therapeutic target." (PMID 40421201, 2025).
renal cell carcinoma (3 papers, 2014 to 2021). "The aim of the present study was to determine whether NFAT5 is also involved in the development of renal cell carcinoma (RCC)." (PMID 25152734, 2014). "Since VHL mutation alone did not induce renal cell carcinoma in mice model it might be interesting to test if a VHL and NFAT5 double KO mouse would develop a renal cell carcinoma." (PMID 34233711, 2021).
ulcerative colitis (3 papers, 2018 to 2025). An inflammatory bowel disease involving the mucosal surface of the large intestine and rectum. "Previous studies have reported reduced NFAT5 expression in rectal biopsies from patients with active ulcerative colitis and Crohn’s disease." (PMID 40663408, 2025). "However, the exact role of NFAT5 in ulcerative colitis pathogenesis requires further investigation of the complex interplay between NFAT5 and ERS-related genes." (PMID 37287987, 2023).
arteriosclerosis (2 papers, 2020 to 2021). A vascular disorder characterized by thickening and hardening of the walls of the arteries. "Overall, these results imply that targeting miR-223/NFAT5 axis can be probably exploited for therapeutic benefits to arteriosclerosis." (PMID 33373321, 2020).
atopic dermatitis (2 papers, 2023 to 2025). "The expression of claudin, cyclin B1, cyclin D1, filaggrin, phospho-histone H2AX, kallikrein 7, Ki67, loricrin, NFAT5, and periplakin was assessed on punch biopsies obtained from eight psoriasis and six atopic eczema patients." (PMID 40559228, 2025).
cardiac failure (2 papers, 2011 to 2021). "Taken together, these facts suggest that cardiac failure contributed to the edema and lethality for NFAT5−/− embryos." (PMID 21765887, 2011). "Cardiac failure is most likely responsible for the peripheral edema and death of NFAT5−/− embryos at E14.5 days." (PMID 21765887, 2011).
Chagas disease (2 papers, 2021 to 2024). A parasitic infection caused by Trypanosoma cruzi. "We identified Bcl2, Gsk3, Nfat5, and Nfatc1 as key players in Chagas disease pathogenesis, and our bioinformatics analysis identified 15 signaling pathways related to Chagas disease development." (PMID 39770386, 2024).
corneal edema (2 papers, 2023 to 2025). "Based on the findings of this study, we propose that loss of NFAT5 results in higher numbers of corneal macrophages with increased pinocytotic capacity, leading to a faster resolution of corneal edema after injury." (PMID 36869067, 2023). "The modulation of corneal NFAT5 might be of great clinical relevance, as corneal edema is one of the leading causes of corneal blindness worldwide." (PMID 36869067, 2023). "Depleting NFAT5 in myeloid cells accelerates corneal oedema resolution, indicating that NFAT5 plays a critical role in corneal inflammation." (PMID 40421201, 2025). "In this study, we present NFAT5 as a new factor regulating the resolution of corneal edema after PCI." (PMID 36869067, 2023). "Based on these findings, we conclude that NFAT5 deficiency-driven accelerated resorption of corneal edema is not linked to changes in lymphatic vessel architecture." (PMID 36869067, 2023). "NFAT5 deficiency did not alter corneal thickness in steady state; however, loss of NFAT5 led to accelerated resorption of corneal edema after PCI." (PMID 36869067, 2023). "Furthermore, NFAT5 in macrophages was crucial for controlling corneal fluid balance and the extent of and recovery from corneal edema." (PMID 36869067, 2023).
COVID-19 (2 papers, 2022 to 2024). A disease caused by infection with severe acute respiratory syndrome coronavirus 2. "This suggests that the remaining CpGs (annotated in genes such as CCDC61, CD38, FAM38A, LAT, TREX1 or NFAT5, among others) differentially contribute to similarities between COVID-19 progression and SADs, some of them regulating the activation and differentiation of T and B lymphocytes." (PMID 35933486, 2022).
endometrial cancer (2 papers, 2024 to 2025). Primary or metastatic malignant neoplasm involving the endometrium (mucous membrane that lines the endometrial cavity). "In summary, our study indicates that high levels of NFAT5 are associated with more aggressive endometrial cancers." (PMID 38612478, 2024). "The present study explored the expression and function of the transcription factor NFAT5 in endometrial cancer." (PMID 38612478, 2024). "As a result, NFAT5 expression is more abundant in high-grade than in low-grade endometrial cancer tissue." (PMID 38612478, 2024). "To gain further insight into the role of NFAT5 overexpression in high-grade endometrial cancer, we used Ishikawa cells, a well-used model of adenocarcinoma cancer." (PMID 38612478, 2024). "Furthermore, NFAT5 plays a pivotal role in endometrial cancer, where the NFAT5-COX-2 signalling axis is critical for tumor progression." (PMID 40421201, 2025). "As apparent from immunohistochemistry in low-grade (G1, G2) endometrial cancer tissue, NFAT5 staining showed low to intermediate cytoplasmic intensity (score 1) in the tumor cells, which is less than the moderate staining in neighboring endothelial cells (score 2) serving as an internal reference." (PMID 38612478, 2024). "Our findings suggest that activation of NFAT5—HIF-1α—COX2 axis could promote endometrial cancer progression." (PMID 38612478, 2024). "The present study thus explored whether NFAT5 is expressed in human endometrial cancer tissue, whether NFAT5 expression in endometrial cancer cells is sensitive to HIF-1α, and investigated whether NFAT5 activation influences the expression of HIF-1α and COX2 signaling cascade in EnCa pathogenesis." (PMID 38612478, 2024). "In our study, we report that expression of NFAT5 was significantly higher in more aggressive (G3) endometrial cancer tissues than in corresponding non-tumor, low-grade (G1) tissues." (PMID 38612478, 2024).
intervertebral disc degeneration (2 papers, 2023 to 2025). "miR-31 downregulates NFAT5, increasing NP cell viability and reducing cell death, which is associated with protection against intervertebral disc degeneration." (PMID 40421201, 2025).
intrahepatic cholangiocarcinoma (2 papers, 2025). A carcinoma that arises from the intrahepatic bile duct epithelium in any site of the intrahepatic biliary tree. "Additionally, in intrahepatic cholangiocarcinoma (ICC), the upregulation of nuclear factor of activated T cells 5 (NFAT5) increases GLUT1 expression and induces gemcitabine (GEM) resistance." (PMID 40264038, 2025).
osteoporosis (2 papers, 2022). A condition of reduced bone mass, with decreased cortical thickness and a decrease in the number and size of the trabeculae of cancellous bone (but normal chemical composition), resulting in increased fracture incidence. "Meanwhile, NFAT5 expression decreased in patients with osteoporosis." (PMID 35587369, 2022). "In summary, this study suggests that KCNQ1OT1, as a sponge for miR-128-3p, inhibits the osteoclast differentiation of RAW 264.7 cells through NFAT5 activation, which might provide a promising therapeutic approach to the prevention and treatment of osteoporosis." (PMID 35587369, 2022). "Target genes with the highest number of miRNAs were DGKH, TNRC6B, ZNF704, INO80D and NFAT5, but according to the literature, none of these were ever directly associated with PTH or osteoporosis." (PMID 36011354, 2022).
peripheral nerve injury (2 papers, 2024 to 2025). Injury to a peripheral nerve. "Consequently, NFAT5 signaling emerges as a potential therapeutic target for treating neuropathic pain induced by peripheral nerve injury." (PMID 38195869, 2024).
preeclampsia (2 papers, 2021 to 2024). Preeclampsia is a hypertensive disorder of pregnancy that is characterized by new-onset hypertension with proteinuria presenting after 20 weeks of gestation, and depending on mild or severe forms may initially present with severe headache, visual disturbances, and hyperreflexia. "Further target gene prediction revealed that nuclear factor of activated T-cells 5 gene was included among the transcriptional targets of preeclampsia-modulated microRNAs." (PMID 33923172, 2021).
Ureteral obstruction (2 papers, 2024 to 2025). Obstruction of the flow of urine through the ureter. ", since they observed a severe effect on kidney injury after unilateral ureteral obstruction in NFAT5‐KO mice compared to control and with other studies where experimentally induced kidney injury was found to be more severe in Nfat5‐deficient models." (PMID 39874047, 2025). "Notably, they observed that Nfat5‐KO significantly worsened fibrosis in the renal medulla, along with heightened immune response activation following unilateral ureteral obstruction." (PMID 39874047, 2025). "NFAT5 deletion from proximal tubule epithelial cells (PTEC) exacerbated kidney fibrosis and inflammation in the unilateral ureteral obstruction model, implicating a pathophysiological role for this transcription factor in the dysregulation of innate and adaptive immune responses in PTEC." (PMID 39595620, 2024).
viral myocarditis (2 papers, 2017 to 2025). Myocarditis that is caused by an infection with a viral agent. "Loss of NFAT5 leads to desmoplakin downregulation and desmosomal disruption, which may underlie the cardiac dysfunction in viral myocarditis." (PMID 41156753, 2025). "In a murine model of viral myocarditis, we observed that treatment with hypertonic saline or mannitol solution upregulated NFAT5 and iNOS expression, inhibited CVB3 replication and reduced tissue damage in the heart." (PMID 29220410, 2017). "Combined, these previous findings inspired us to link NFAT5 to anti-CVB3 activity, a virgin field for studies of both NFAT5 and viral myocarditis." (PMID 29220410, 2017). "In this study, we aimed to understand the mechanism by which NFAT5 interferes with infection of Coxsackievirus B3 (CVB3), a major cause of viral myocarditis." (PMID 29220410, 2017). "Thus, upregulating NFAT5 expression with identified hypertonic-inducing agents is a promising strategy to develop therapeutics for viral myocarditis." (PMID 41156753, 2025). "Thus search for other hypertonic agents to induce upregulation of NFAT5 may be a strategy for the development of effective therapy against viral myocarditis." (PMID 29220410, 2017). "This study elucidates the role of NFAT5 in preserving desmosomal integrity during CVB3 infection, and underscores the therapeutic potential of cyclodextrins in the treatment of viral myocarditis." (PMID 41156753, 2025).
acquired immunodeficiency syndrome (1 paper, 2025). "Notably, NFAT5 acts as a host factor-viral enhancer for HIV-1 subtype viruses in HeLa CD4+ cells and THP-1 monocytes, suggesting that disrupting this interaction could inhibit viral replication and potentially slow acquired immunodeficiency syndrome (AIDS) progression." (PMID 40421201, 2025).
acute lymphoblastic leukaemia (1 paper, 2025). "In acute lymphoblastic leukaemia cells, purple sweet potato anthocyanins inhibit NFAT5 activity, inducing calcicoptosis, a calcium overload-driven cell death mechanism." (PMID 40421201, 2025). "Under hyperosmolar conditions, NFAT5 drives the activation of paired box 2 (PAX2) in coordination with PAX5, in pre-B acute lymphoblastic leukaemia cells." (PMID 40421201, 2025).
adrenocortical carcinoma (1 paper, 2025). "NFAT5 is overexpressed in a cohort of 25 patients with adrenocortical carcinoma, where ten exhibited NFAT5 amplification and overexpression, confirmed by qPCR." (PMID 40421201, 2025).
asthma (1 paper, 2015). "The remaining 4 target genes were assessed based on previous literature: ATXN1 has been associated with asthma, NFAT5 is implicated in the regulation of proinflammatory cytokines, NR3C1 is a target for steroid-based asthma treatments and TAB2 is a validated miR-155-5p target." (PMID 26693910, 2015).
Brain atrophy (1 paper, 2024). Partial or complete wasting (loss) of brain tissue that was once present. "Evaluation of brain atrophy, whose extent is predominantly determined by brain tissue damage occurring in the acute phase, four weeks upon onset of stroke revealed significantly reduced loss of brain tissue in Nfat5(EC)−/− mice as compared to Nfat5fl/fl animals." (PMID 39710754, 2024). "Considering that loss of endothelial NFAT5 did neither affect edema formation, inflammation and angiogenesis nor did this further alter structural and functional parameters at later stages after stroke such as brain atrophy, we concluded that NFAT5 acts in the immediate early phase after MCAO." (PMID 39710754, 2024). "While loss of endothelial Nfat5 did not evoke any phenotypic abnormalities in mice under control conditions, infarct volumes, neurological deficits and the degree of brain atrophy were significantly pronounced following MCAO as compared to control animals (Nfat5fl/fl)." (PMID 39710754, 2024).
breast tumor (1 paper, 2022). "There was enhanced breast tumor progression in CD4-NFAT5-KO mice, suggesting that NFAT5 knock out abrogated the inflammatory anti-tumor activation of CD4+T cells." (PMID 35741331, 2022).
CAEBV infection (1 paper, 2022). "We present the cases of two pediatric patients with NFAT5 haploinsufficiency and EBV susceptibility: one with CAEBV infection with hepatitis and enterocolitis, and one with fatal HLH." (PMID 36238298, 2022).
cerebral infarction (1 paper, 2025). An ischemic condition of the brain, producing a persistent focal neurological deficit in the area of distribution of the cerebral arteries. "In addition, suppression of NFAT5 in microglia mitigated neuronal loss, reduced the extent of cerebral infarction, and improved limb grip strength in mice after MCAO modeling." (PMID 40831534, 2025). "Here, our findings indicated that microglial NFAT5 knockdown reduced the expression of pro-inflammatory factors, microglial activation, and neutrophil infiltration, ultimately ameliorating cerebral infarction and neurological deficits in mice following MCAO." (PMID 40831534, 2025). "The MCAO modeling induced substantial brain infarction, whereas specific NFAT5 knockdown significantly reversed MCAO-induced cerebral infarction." (PMID 40831534, 2025). "In this work, our results showed that suppression of microglial NFAT5 attenuated neuroinflammation, ameliorated neuronal apoptosis around the penumbra region, and reduced the extent of cerebral infarction." (PMID 40831534, 2025). "This suggests that microglial NFAT5 knockdown effectively mitigates the extent of brain infarction following MCAO modeling." (PMID 40831534, 2025). "Therefore, NFAT5 may mediate neuronal apoptosis and the extent of cerebral infarction via regulating neuroinflammation around the penumbra region." (PMID 40831534, 2025).
Cerebral ischemia (1 paper, 2024). Restriction of arterial blood supply to the brain associated with insufficient oxygenation to support the metabolic requirements of the tissue. "Collectively, our work revealed a critical role of endothelial Nfat5 for limiting infarct development after brain ischemia underlining its relevance in the context of organotypic stress responses." (PMID 39710754, 2024). "Our findings imply that loss of endothelial Nfat5 causes a reperfusion deficit after brain ischemia most likely by a general depletion of Kir2.1 in the brain endothelium." (PMID 39710754, 2024). "In the context of brain ischemia, the transcriptional regulation of gene expression by NFAT5 appears to be similarly relevant for adequate stress responses of the vasculature." (PMID 39710754, 2024). "As the infarct size is greatly influenced by the level of reperfusion after MCAO, impairment in perfusion recovery as observed in Nfat5(EC)−/− versus Nfat5fl/fl mice is a plausible explanation for the exacerbated consequences of brain ischemia." (PMID 39710754, 2024). "To test our hypothesis, we applied a transient cerebral ischemia model in mice, allowing for the inducible endothelial cell-specific knockout of Nfat5 and evaluated the consequences of intermittent brain ischemia on the histological and functional level." (PMID 39710754, 2024).
cervical cancer (1 paper, 2023). A primary or metastatic malignant neoplasm involving the cervix. "TonEBP (NFAT5) was the second top differentially expressed gene (DEG) that was positively correlated with SLC5A3 expression in TCGA cervical cancer cohort." (PMID 37324953, 2023).
cognitive decline (1 paper, 2025). "Additionally, NFAT5 plays a central role in age-related microglial activation and cognitive decline." (PMID 40421201, 2025).
congestive heart failure (1 paper, 2014). Failure of the heart to pump a sufficient amount of blood to meet the needs of the body tissues, resulting in tissue congestion and edema. "We scrutinized this hypothesis by investigating stretch-induced nuclear translocation of NFAT5 in VSMCs which were treated with etomoxir—an inhibitor of the mitochondrial carnitine palmitoyltransferase 1 that is tested in clinical trials for its capacity to treat congestive heart failure." (PMID 25520667, 2014).
dermatomyositis (1 paper, 2018). Dermatomyositis (DM) is a type of idiopathic inflammatory myopathy characterized by evocative skin lesions and symmetrical proximal muscle weakness. "In muscle biopsies from dermatomyositis and polymyositis patients, NFAT5 colocalized with HDAC6, while in IBM, this was often absent." (PMID 29515464, 2018). "In vivo localization and expression of NFAT5 were studied in muscle biopsies of patients diagnosed with polymyositis (n = 6), dermatomyositis (n = 10), inclusion body myositis (n = 11) and were compared to NFAT5 localization and expression in non-myopathic controls (n = 13)." (PMID 29515464, 2018).
diabetes insipidus (1 paper, 2025). A disorder characterized by excretion of large amounts of urine, accompanied by excessive thirst. "A recent study using a CD principal cell (PC)‐specific Nfat5 knockout (Nfat5‐KO) mouse revealed that NFAT5 loss is linked to a diabetes insipidus‐like phenotype and significant changes in gene expression." (PMID 39874047, 2025). "Recently, using a targeted deletion strategy, we generated a PC‐specific Nfat5‐KO mouse model using an Aqp2‐driven Cre‐deleter (Aqp2Cre+/−Nfat5fl/fl) that results in a diabetes insipidus‐like phenotype." (PMID 39874047, 2025).
endometrial tumor (1 paper, 2024). "Immunostaining was performed on formalin fixed, paraffin-embedded (FFPE) archival endometrial tumor tissue and investigated for NFAT5 expression." (PMID 38612478, 2024). "The present study explored whether NFAT5 is expressed in endometrial tumors and if NFAT5 participates in cancer progression." (PMID 38612478, 2024). "In conclusion, NFAT5 is expressed in high-grade endometrial tumor tissue and upregulates many genes including HIF1A and PTGS2, which may participate in malignant tumor pathogenesis." (PMID 38612478, 2024).
endometrioid carcinomas (1 paper, 2024). "In contrast, NFAT5 expression shows a strong and block-like expression pattern in high-grade endometrioid carcinomas (G3) with particularly strong staining in the perivascular area and on the leading edge." (PMID 38612478, 2024).